IL4 (interleukin 4)
Diseases named in the same sentence as IL4 in open-access papers (continued):
Sharing a sentence is not in itself a finding about the gene and the disease.
tumor (continued). "Administration of an IL-4 blocking antibody did not significantly affect LLC1 tumor growth and had a minor effect on B16F10 growth, suggesting that the delay in tumor growth in CD4Nlrp3-/- mice is not solely due to impaired Th2 differentiation and IL-4 production." (PMID 40195474, 2025). "Indeed, all activators (LPS, IL-4, WGP, and tumor supernatant) upregulated Dectin-1, but not TLR-2 and TLR-4, highlighted an enhancement of Dectin-1 on the non-specific activations of macrophages, perhaps as a preparation for the possible following activations." (PMID 36142859, 2022). "In the present study, we found that the expression of IL-4, IL-6, TNF-α, and IFN-γ but not IL-10 dramatically increased after T cell interaction with peptides+HB100-108/pulsed DCs, indicating that this vaccine design has the ability to activate allogeneic T cells against tumor antigen." (PMID 32322595, 2020). "Similarly, in in vivo experiment on Balb/c mice injected with EMT6/P cells, the combination MET+CUR decreased tumor size but only trends for increase of IFN-γ and for significant decrease of IL-4 were detected, while IL-2 and IL-10 level did not change significantly." (PMID 30959898, 2019). "However it could suggest a non-specific effect of tumor exosomes, which might not be sufficient for effective suppression without the induction of TGF-β1 and IL-4." (PMID 21829629, 2011).
infection (1,745 papers, 2004 to 2026). The state of being infected such as from the introduction of a foreign agent such as serum, vaccine, antigenic substance or organism. "Decreased IL-4Rα positive macrophage recruitment to a site of injury or infection has been linked to the inability to promote IL-4 signalling via IL-4Rα and impairment in induction of IL-4Rα on microglia is noted as a contributing factor to reduced recovery." (PMID 40977748, 2025). "While the Th1 response is associated with host resistance to the parasite, the Th2 response through the expression of IL-4, IL-6, and IL-10 is associated with greater susceptibility to infection." (PMID 40572185, 2025). "Gene expression of pro-inflammatory cytokines IL-1β, IL-2, IL-4, and IL-6, as well as IFNγ was significantly upregulated in nasal turbinates in response to infection with all VOCs, with the Gamma variant inducing the highest inflammatory response." (PMID 40295859, 2025). "IL-4 enhances IFN-γ production in the later stages of infection; however, its absence can lead to increased susceptibility to severe toxoplasmic encephalitis." (PMID 40732170, 2025). "It contributes to protection from infection, while the Th2 immune response, characterized by the production of IL-4, IL-10, TGF-β, IL-6, and others, is associated with disease progression and with parasite growth." (PMID 40666521, 2025). "They found that by activating IL-4-pretreated, resting T cells several days after infection with IN-deficient HIV, de novovirus was generated from unintegrated DNA without the help of integrated provirus." (PMID 40098202, 2025). "Mice deficient in Irf4 in CD11c+ cells secrete less IL-4, IL-5, and IL-13 both in the SI and colon after infection with the parasite Schistosoma mansoni, and a similar outcome is observed after infection with T. muris and Nippostrongylus brasiliensis." (PMID 41028655, 2025). "We found that adjuvanting QIV with AddaVax resulted in a type 2-skewed host response to infection, with hallmark type 2 cytokines IL-4, IL-5, and IL-13 present in the lung homogenates of the aQIV group at 5 days post-infection." (PMID 39975920, 2025). "IFN-γ expression is associated with resolving infection in mammals, since this cytokine induces parasite killing by macrophages following nitric oxide release, as well as causing the direct inhibition of IL-4 and IL-10 production." (PMID 41471158, 2025). "This shows that decreased IL-4Ra positive macrophage recruitment to a site of injury or infection has been linked to the inability to promote IL-4 signalling via IL-4Ra, impairment in induction of IL-4Ra on microglia; a contributing factor to reduced recovery." (PMID 40977748, 2025). "Th2 cytokines (IL-4, IL-5 and IL-13) were only associated with infection intensity in the oldest age group aged 14–18 years of age." (PMID 39250522, 2024). "Infection with cytopathic strains caused massive death of IL-4-treated Mo-Mφ, while cells treated with azithromycin developed cytopathic effect, and metabolism was partially reduced compared to mock-infected cells." (PMID 37966797, 2024). "The weight loss has been directly linked to IL-4 mediated events since treating animals with IL-4c had the same effect as an Hb infection and the weight loss, and increased mortality, was reversed in STAT6 knock out animals." (PMID 38950025, 2024). "In Leishmania-susceptible BALB/c mice, il-4 was reported to be elevated after infection, which leads to progressive disease." (PMID 39436890, 2024). "The inability of the WT mice to control the infection was associated with antigen-specific Th2-type responses with higher levels of IgG1, IL-4, IL-13, and total IgE, reduced NO production, and increased arginase activity." (PMID 38392907, 2024). "From a diagnostic perspective, IL-4 can serve as a biomarker for assessing the immune response during infections." (PMID 38251210, 2024).
infection (continued). "The presence of these cytokines indicates pro-inflammatory processes, with IL-6 being associated with the response to infection and tissue damage and IL-4 with the production of immunoglobulin E, regulation of cell proliferation and apoptosis." (PMID 39015324, 2024). "The M2 infection module revealed Chil3, Il4, Cx3cr1, Emr1 and Ccl2 as hubs, while module M6, associated with vaccination, disclosed Prf1, Klrc1, IFN-γ, Ncr1 and Tbx21 as hub proteins." (PMID 39563428, 2024). "infection in vitro, and found that IL-4 deficiency also weakened the anti-apoptotic effect of eosinophils on CD8+ T cells." (PMID 38413575, 2024). "Upon infection with T. trichiura, male IL-4-deficient BALB/c mice were found to exhibit chronic infection, while females displayed acute infection, suggesting that IL-4 plays a genetic-dependent role in the immune response of hosts induced by T. trichiura." (PMID 37637465, 2023). "In CL-causing species, increased IL-4 production has been demonstrated to be associated with susceptibility to infection in mice." (PMID 37569710, 2023). "In fact, a study conducted on genetically resistant C57BL/6 mice infected with L. major Seidman strain reported the deactivation of M1 macrophages by eosinophil-derived IL-4, rendering these mice susceptible to infection." (PMID 37908348, 2023). "IL-10 plays an important role as an anti-inflammatory cytokine by preventing pathogenic infection and excessive immune response, and IL-4 regulates the immune responses." (PMID 37006463, 2023). "After the onset of oviposition following challenge infection, fibrosis-associated genes (il-4, il-13 and acta-2) are increasingly expressed." (PMID 36923416, 2023). "Seven days post-Plasmodium yoelii 17XL infection, higher levels of IL-4, IL-10, IL-12, and IL-17 were observed in MIF-deficient mice than WT mice." (PMID 38275363, 2023). "For infection with N. brasiliensis, we tested mice doubly deficient in Il4 and Il13 and confirmed a causal role of IL-4 and/or IL-13 in inhibition of both Th1 and Th17 differentiation in vivo after MINCLE-dependent immunization." (PMID 36753434, 2023). "Serum IL-4 level is upregulated in bacterial infection-induced systemic inflammatory response syndrome and can be a good predictor of infection-related mortality risk." (PMID 35356501, 2022). "In contrast, increased resistance to P. chabaudi adami infection in Mif -/- mice was associated with increased IFN-γ production and reduced IL-4 and IL-10 in early infection." (PMID 36093199, 2022). "This is in contrast to findings in mice, where tick feeding induced the capacity for IL-4 production and Th2 responses were associated with decreased bacterial load upon infection with B. burgdorferi sensu stricto (Bbss)." (PMID 36166299, 2022). "It is in the chronic phase when more pulmonary damage is produced, and this is associated with an exacerbated IL-4 production by Th2 cells, which breaks the necessary Th1/Th2 balance to control the infection." (PMID 36678397, 2022). "In contrast, severe metastatic infections are developed in susceptible mice such as BALB/c strain in which the infection is disseminated to other organs including the viscera, while their T-cells produce IL-4, IL-5, and IL-13 cytokines (i.e., the Th2 profile)." (PMID 35090305, 2022). "In this work, similar to our previous report, we demonstrated that HPV infection promotes chronic inflammation through high levels of IFN-γ, IL-1β and IL-6 caused by single or multiple infection, and even an increment of IL-4, as in a preliminary study." (PMID 35739948, 2022). "If the response of anti-inflammatory cytokines such as IL-4 and IL-10 overcompensate for the initial wave of inflammation, it opens susceptibility for future infection or inability to fight the current one." (PMID 35814217, 2022).
infection (continued). "Flow cytometry analysis showed that the increasing percentage of Th2 cells, which mainly secrete IL-4 cytokines in spleen cells, was significantly lower in PKCλ/ι-deficient mice compared with wild-type mice after infection (P < 0.05)." (PMID 35505421, 2022). "The level of IL-4, a Th2 hallmark cytokine, was significantly lower in the BCGΔRS01790 infection than in the other two groups throughout the infection period." (PMID 35281073, 2022). "OM-85 IN treatment given 3 days prior to infection protected against weight loss at days 2 and 3 post-infection, significantly reduced viral load, decreased perivascular and peri bronchial inflammation, and reduced IL-4 production in the lung." (PMID 36479289, 2022). "In susceptible, BALB/cAnN mice, a 12-fold increase in IL-4 expression was observed on day 5 post-infection, while more modest increases were observed for the expression of IFN-γ and IL-12b." (PMID 33928043, 2021). "The IL-4Rα pathway, a common receptor for IL-4 and IL-13 signaling, is essential in generating anti-inflammatory responses and mediating susceptibility to infection by Leishmania parasites causing CL in mice." (PMID 35154068, 2021). "IL-4 production by Tfh cells is acquired during the associated stages of infection that parallels GC development, either during helminth or viral infection." (PMID 33983946, 2021). "This relative reduction of susceptibility to infection was paralleled by a more robust humoral response against parasite antigens, elevated serum IL-4 and liver cytokines." (PMID 34956183, 2021). "Conversely, in WNV and other infections, elevated levels of IL-4 appear to be associated with less-severe forms of the disease." (PMID 33671257, 2021). "In fact, during pathogen infection, early cytokines responses involving IL-4 and IL-10 increase host susceptibility, whereas responses involving IL-12 and IFN-γ are important for resistance." (PMID 34035796, 2021). "Mice were susceptible to the challenge infection despite the development of a Th2 phenotype with elevated levels of IL-4 and IL-13 gene expression but low levels of endogenous expression of IL-25." (PMID 33276813, 2020). "It is well established that a dominant Th1 response (IFN-γ, a hallmark Th1 cytokine) provides resistance, whereas a dominant Th2 response (IL-4, a hallmark Th2 cytokine) confers susceptibility during infection." (PMID 32948646, 2020). "In support of this, both L. major susceptible BALB/c and resistant C57BL/6 mice produce IL-4 in the early phase of infection, however this is sustained in susceptible mice but redirected in resistant mice by IL-12-dependent mechanisms." (PMID 33415318, 2020). "IL-4 and IL-10 are key regulators of the immune response and downregulate Th1 response-driven inflammatory reactions, protecting the host from infection-associated immunopathology to maintain placental homeostasis." (PMID 32552750, 2020). "IL-4 neutralization (via anti–IL-4 Ab) results in resistance to Leishmania spp., demonstrating a pathogenic role for IL-4 during infection." (PMID 32948646, 2020). "For instance, the Th1/Th2 dichotomy and the importance of IL-4 in mediating susceptibility to infection were discovered using a particular L. major strain." (PMID 31555609, 2019). "A recent review of intestinal helminth infection also showed redundancy between IL-4 and IL-13, indicating that IL-13 deficiency can be compensated for by IL-4 in murine models of infection." (PMID 30759882, 2019). "Considering that type-2 immunity has been associated with resistance to infection by gastrointestinal nematodes, we next analyzed the gene expression of classical Th2 cytokines IL-4, IL-5, IL-13." (PMID 31862904, 2019). "In accordance with the myeloid cell data, the increase in the type-2-associated cytokine, IL-4, occurred only after infection as uninfected IL-33-treated mice had equivalent levels of IL-4 relative to controls." (PMID 31221971, 2019).
infection (continued). "In experimental VL, IFN-γ and IL-12 cause the protective condition while IL-4 and IL-10 enhance the progression of infection." (PMID 30834079, 2019). "IL-4 production is similar in the initial phase of infection in both susceptible and resistant mice; however, the production of this cytokine in resistant mice is transient." (PMID 30150896, 2018). "Experimentally infected cattle have increased IL-2 and IFN-γ production in the first 2 to 3 weeks postinfection, while our study suggests that the early stages of natural infection are associated with increased IL-4 production and IL-5 transcription." (PMID 28993458, 2018). "In fact, MDM were found to be susceptible to infection and supported a high level of virus replication which was further enhanced by IL-4 polarization." (PMID 30282716, 2018). "In contrast, the S. aureus induced an increase of the percentage of gated CD4 + IL-4 + T cells at days 7 and 14 post-infection in WT mice, which was reduced by ST2 deficiency." (PMID 29867945, 2018). "By analyzing the signaling pathways of IL-4/IL-13, which are related to the susceptibility to infection, we noticed shared components with the IGF-I pathway." (PMID 30150896, 2018). "In contrast, during infection, the opposite relationship was frequently found, with IL-4, IL-13, CCL5, CCL20 and CCL24 levels associated with less severe reductions in both FVC and FEV1." (PMID 30463560, 2018). "Cutaneous Curdlan application was associated with a modulation of the IFN-/IL-4 ratios at day 10 and 28, indicating a shift toward a pronounced Th1 and a dampened Th2 response at day 28 after infection." (PMID 29535708, 2018). "In contrast, IL-4, IL-10 and IL-13 act as downregulators of the cellular immune response, inhibiting T-cell proliferation, and are associated with impaired infection control and a poor outcome." (PMID 28486489, 2017). "Infection of the IL-4 stimulated mDCs caused a trend of downregulation for both viruses, with the VR-2332 (comparisons #16–21) exhibiting mostly immune gene downregulation." (PMID 28727780, 2017). "In murine models, sialylated IgGs bind to DC-SIGN, inducing the production of IL-33, an infection-linked cytokine that activates basophils to produce IL-4, leading to the upregulation of the inhibitory Fc receptor FcγRIIb." (PMID 29098000, 2017). "Nevertheless, there remains a strong association between lower levels of IL4 during infection and worm loss." (PMID 29253882, 2017). "To investigate a putative autocrine role of IL-4 signaling on keratinocytes at the site of infection, we generated C57BL/6 mice deficient for IL-4Rα expression selectively in keratinocytes." (PMID 29067025, 2017). "The production of IL-4 and IL-13 was higher in spleen cells of infected Ebi3-deficient mice on day 7 post-infection, which probably generated an ideal microenvironment required to the differentiation of alternatively activated macrophages." (PMID 29033934, 2017). "The dominance of a Th2 response in patients who are at higher risk of infection was confirmed by the significantly lower Th1/Th2 ratio as represented by IFNγ/IL4 levels seen on univariate analysis." (PMID 29051761, 2017). "By contrast, the Th2 response with high production of IL-4 and IL-13 is associated with susceptibility to infection." (PMID 28567039, 2017). "Initial control of L. major during the acute phase of infection in IL-4−/−-deficient mice and IL-4Rα−/−-deficient BALB/c mice is equivalent, with both strains of mice showing reduced footpad swelling, parasite loads and type 1 antibody responses." (PMID 29176972, 2017). "In contrast, challenge with large numbers of parasites in the footpad of BALB/c mice generates a progressive infection associated with parasite-specific responses mediated by IL-10 and IL-4." (PMID 28558043, 2017). "IL-4 treatment reversed the infection-induced loss of staining for complex I and IV (P < 0.05), and IL-6 provided protection against loss of complex IV (P < 0.05)." (PMID 26481427, 2015).